TSPAN1 (tetraspanin 1)
Description:
Structural component of specialized membrane microdomains known as tetraspanin-enriched microdomains (TERMs), which act as platforms for receptor clustering and signaling. Participates thereby in diverse biological functions such as cell signal transduction, adhesion, migration and protein trafficking. Regulates neuronal differentiation in response to NGF by facilitating NGF-mediated activation of NTRK1/TRKA receptor tyrosine kinase and subsequent downstream signaling pathways (By similarity). Plays a role in the inhibition of TNFalpha-induced apoptosis. Mechanistically, inhibits the NF-kappa-B signaling pathway by blocking phosphorylation of CHUK. Also promotes the stability of the thiamine transporter 1/SLC19A2 in intestinal epithelial cells leading to an increase of thiamine uptake process.
Synonyms: Tspan-1; NET-1; NET1; TM4C; TM4SF
Tractability: Antibody: UniProt places it where antibodies can reach, with high confidence; its Gene Ontology location is reachable by antibodies, with high confidence; UniProt predicts a signal peptide or a membrane-spanning region.
Gene: Protein-coding gene on chromosome 1 (46,173,794 to 46,185,968, forward strand). Ensembl gene ENSG00000117472.
Subcellular location: Cell membrane; Lysosome membrane
Subcellular location (Human Protein Atlas): Nucleoplasm; Vesicles
Gene Ontology:
Molecular function: protein binding
Biological process: protein stabilization
Cellular component: cytoplasm; extracellular exosome; membrane; perinuclear region of cytoplasm; plasma membrane; vesicle; lysosomal membrane
Genetic constraint (gnomAD): Loss-of-function variants: 23 observed, 28.53 expected, observed/expected ratio (o/e) 0.81, 90% interval 0.58 to 1.14. The upper end of that interval is the gene's LOEUF score, 1.14, which puts it in group 5 of 6, group 1 being the genes least tolerant of losing a copy. Missense variants: 283 observed, 314.8 expected, observed/expected ratio (o/e) 0.9, 90% interval 0.81 to 0.99. Synonymous variants: 115 observed, 121.38 expected, observed/expected ratio (o/e) 0.95, 90% interval 0.81 to 1.11.
Homologues: Orthologues: chimpanzee TSPAN1 (99% identical), macaque TSPAN1 (88% identical), pig TSPAN1 (83% identical), dog TSPAN1 (81% identical), rabbit TSPAN1 (80% identical), guinea pig TSPAN1 (76% identical), rat Tspan1 (74% identical), mouse Tspan1 (73% identical), tropical clawed frog tspan1 (61% identical), zebrafish tspan1 (47% identical). Paralogues in human: TSPAN18 (33% identical), TSPAN8 (30% identical), CD82 (30% identical), TSPAN9 (29% identical), TSPAN11 (29% identical), TSPAN2 (28% identical), TSPAN4 (28% identical), CD151 (27% identical), CD9 (26% identical), CD37 (26% identical), CD81 (26% identical), TSPAN5 (26% identical), and 20 more.
Diseases named in the same sentence as TSPAN1 in open-access papers:
TSPAN1 is named in the same sentence as 45 diseases in open-access papers, as found by Europe PMC text mining. Sharing a sentence is not in itself a finding about the gene and the disease. The quoted sentences say what the papers report.
pancreatic cancer (21 papers, 2019 to 2025). "Surprisingly, in previous studies, it has been proved that all of our defined switch genes, including Lamc2, Klk1, Nqo1, Aox1, Tspan1, and Cxcl12, are closely associated with the pancreatic cancer’s progression." (PMID 35180880, 2022). "Mutations in the LIR TSPAN1 motives resulted in a loss of ability to induce autophagy and promote the proliferation of pancreatic cancer." (PMID 34680441, 2021). "Tspan1 expression was demonstrated to be upregulated in pancreatic cancer in vitro and in vivo, and Tspan1 deletion decreased the proliferation of pancreatic cancer cells." (PMID 38649381, 2024). "MiR-216a is involved in the progression of pancreatic cancer through the two-axis, including miR-216a/tetraspanin-1 (TSPAN1)/integrin alpha-2 precursor (ITGA2) and LINC01133/miR-216a-5p/translationally-controlled tumor protein (TPT1)." (PMID 38559560, 2024). "This study identifies and validates a novel five-gene transcriptomic signature (LAMC2, TSPAN1, MYO1E, MYOF, and SULF1) as both diagnostic biomarkers and potential drug targets for pancreatic cancer." (PMID 39850570, 2024). "For example, Tspan1 and Tspan8 are upregulated in pancreatic cancer and colorectal cancer, respectively, and promote tumor cell invasion, migration, and autophagy." (PMID 38649381, 2024). "Each of the fatty acid synthase/Wnt, miR-148a/Wnt10b, Linc00261/miR-552-5p/FOXO3, and miR-454/FAM83A/TSPAN1 axes can be valuable biomarkers and potential therapeutic targets in pancreatic cancer." (PMID 38559560, 2024). "Tspan1, a novel member of the TM4SF, is abundantly expressed in many types of cancers, including liver, gastric, colon, esophageal, and especially pancreatic cancer." (PMID 38389703, 2024). "In recent studies, Tspan1 has been demonstrated to promote the metastasis and growth of pancreatic cancer cells by positive regulation the FAM110A/HIST1H2BK/G9a axis." (PMID 38389703, 2024). "Tspan1, identified as a HUB gene closely associated with pancreatic cancer, exhibits significant correlations with tumor histological grade, T stage, clinical stage, and overall survival." (PMID 38649381, 2024). "TSPAN1 is also overexpressed in pancreatic cancer via family members with sequence similarity 83 (FAM83A) in the canonical WNT-Catenin Beta 1 (CTNNB1) signaling pathway." (PMID 38559560, 2024). "FAM83A-dependent Wnt/β-catenin activation can enhance the expression of TSPAN1 to activate autophagy and promote the proliferation of pancreatic cancer cells." (PMID 36829596, 2023). "High TSPAN1 expression was correlated with poor overall survival of pancreatic cancer patients, and TSPAN1 promote the proliferation of pancreatic cancer cells." (PMID 36941633, 2023). "Our investigation was performed in the Drug Bank database and showed that some drugs, including Peroxisomal acyl-coenzyme A oxidase 1 and Methocarbamol, are designed for Aox1 and Tspan1, as therapeutic anti pancreatic cancer targets, respectively." (PMID 35180880, 2022). "Recent studies have shown that TSPAN1 expression levels are elevated in pancreatic cancer and that reducing its expression reduces the proliferation of pancreatic cancer cells in vitro and in vivo." (PMID 34680441, 2021). "TSPAN1 has been reported to regulate the progression of many human cancers, including gastric cancer, pancreatic cancer and cervical cancer." (PMID 31182966, 2019). "Notably, the miR454-FAM83A-TSPAN1 axis, with TSPAN1 acting as a positive autophagy regulator and a target of microRNA454, has been shown to facilitate autophagy and influence pancreatic cancer cell proliferation." (PMID 40176193, 2025). "Also in pancreatic cancer, Tspan1 was found to be negatively regulated by miR-573 and miR-216a, and upregulated Tspan1 contributed to the metastasis and proliferation of cancer cells." (PMID 38389703, 2024).
pancreatic cancer (continued). "In contrast, some miRNAs restrain cancer progression through targeting Tspans [for example, CD151 with miR-199a-3p and miR-124 in hepatocellular carcinoma, Tspan1 with miR-573 and miR-216a in pancreatic cancer, with miR-194-5p in cholangiocarcinoma, and with miR-573 in gastric cancer]." (PMID 38389703, 2024). "Similarly, Tspan1 contributes to pancreatic cancer cell migration and invasion through promoting MMP2 expression via PLCγ." (PMID 38389703, 2024). "TSPAN1 is frequently upregulated in cholangiocarcinoma, pancreatic cancer, and gastric cancer." (PMID 36941633, 2023). "Meanwhile, TSPAN1 promotes pancreatic cancer cell migration and invasion by upregulating MMP2." (PMID 36941633, 2023). "TSPAN1 expression was correlated with poor overall survival of pancreatic cancer patients." (PMID 34680441, 2021). "Another study indicated the effects of TSPAN1 on the autophagy of pancreatic cancer." (PMID 34852709, 2021). "These preliminary results suggest that the combination of EpCAM and TSPAN1 could help increase the recovery of isolated pancreatic tumor cells from pancreatic cancer patient’s blood." (PMID 35582043, 2020). "Tspan1 regulates MMP2 expression through PLCγ and inhibits migration and invasion of pancreatic cancer cells." (PMID 38649381, 2024). "In pancreatic cancer, TSPAN1 (tetraspanin 1) is upregulated by the activation of Wnt/β-catenin to promote cancer proliferation." (PMID 38584262, 2024). "This leads us to propose a new oncogenic TSPAN1/FAM110A/HIST1H2BK/G9a axis in PDAC that is involved in the modulation of tumor progression and represents a novel therapeutic approach for pancreatic cancer treatment." (PMID 35154458, 2022). "Collectively, the newly identified TSPAN1/FAM110A/HIST1H2BK/G9a axis promotes PDAC progression and represents a novel therapeutic strategy against pancreatic cancer." (PMID 35154458, 2022). "They showed that TSPAN1 promoted autophagy flux and mediated cooperation between WNT-CTNNB1 signaling and autophagy in pancreatic cancer." (PMID 34852709, 2021). "Higher levels of TSPAN1, TMPRSS4, SDR16C5 and CTSE expression were observed in pancreatic cancer than in normal pancreatic tissue (paired t-test, P < 0.0001)." (PMID 33815409, 2021). "Then, survival analysis, Cox univariate and multivariate analysis results indicated that the expression of TSPAN1 and ERBB3 was both negatively correlated with the prognosis of pancreatic cancer, especially those with N1 and/or G1." (PMID 34321959, 2021). "For instance, TSPAN1 has been shown to promote autophagy via the MIR454–FAM83A–TSPAN1 regulatory axis and facilitates the crosstalk between WNT–CTNNB1 signaling and autophagic pathways in pancreatic cancer." (PMID 40443671, 2025). "We found that TSPAN1 and ERBB3 could be independent predictors of poor survival in pancreatic cancer." (PMID 34321959, 2021). "TSPAN1 could up-regulate matrix metalloproteinase 2 (MMP2) through PLCγ to promote migration and invasion of pancreatic cancer cells." (PMID 34852709, 2021). "In good agreement, the overexpression of TSPAN1 in human cancer vs. adjacent non-cancerous tissue has been widely documented in cholangiocarcinoma, skin squamous cell carcinoma, esophageal carcinoma, ovarian carcinomas, prostate cancer, pancreatic cancer and gastric carcinoma." (PMID 33167355, 2020).
gastric cancer (15 papers, 2011 to 2025). A primary or metastatic malignant neoplasm involving the stomach. "Knockdown of Tspan1 in colon and gastric cancer cells elicits G1/G0 phase arrest and inhibits cell proliferation, highlighting its tumor-suppressive potential." (PMID 38649381, 2024). "TSPAN1 also significantly promotes the proliferation and invasion of colon cancer cells and gastric cancer cells with unrevealed mechanism." (PMID 36941633, 2023). "This miR-573/TSPAN1 axis provides a novel perspective on the molecular mechanisms of gastric cancer." (PMID 34222025, 2021). "detected that the expression of TSPAN1 was dramatically increased in gastric cancer tissues, and clarified TSPAN1 as an oncogene to promote gastric cancer cell proliferation and invasion." (PMID 34222025, 2021). "In several studies, overexpression of TSPAN1 was observed in liver cancer, prostate cancer, and gastric carcinoma." (PMID 30382917, 2018). "Similarly, in gastric cancer, TSPAN1 knockdown induces G1/G0 phase block and inhibits invasion and migration." (PMID 38649381, 2024). "Furthermore, Tspan1 was found to be negatively regulated by miR-573, and upregulated Tspan1 contributed to the invasion and proliferation of gastric cancer cells." (PMID 38389703, 2024). "Moreover, they identified that overexpressed miR-573 inhibited growth and invasion, induced G1/G0 arrest of gastric cancer cells through directly targeting 3’UTR of TSPAN1." (PMID 34222025, 2021). "TSPAN1, a member of the transmembrane 4 superfamily, has been reported to be increased in various cancers at the mRNA level, including prostate cancer, gastric carcinoma, and COAD." (PMID 34322151, 2021). "Recently, miR-573 is found to down-regulate the oncogene Tetraspanin 1 (TSPAN1) in gastric cancer." (PMID 27092493, 2016). "Together, TSPAN8, CD151, TSPAN1, and TSPAN4 are overexpressed in gastric cancer tissues and are related to a higher clinical stage and poorer prognosis via interacting with other molecules in TEMs." (PMID 34222025, 2021). "Here, we summarize tetraspanins that enhance the proliferation and invasion of gastric cancer cells, including TSPAN8, CD151, TSPAN1, and TSPAN4." (PMID 34222025, 2021). "TSPAN1 was found to be overexpressed in human CRC, hepatocellular carcinoma, gastric cancer, and ovarian carcinomas." (PMID 25301729, 2014). "Similarly, in gastric cancer, TSPAN1 appeared to regulate CDH11 expression, which, in turn, mediated the interaction between gastric cancer cells and CAFs." (PMID 40777026, 2025). "In general, the expression of TSPAN8, CD151, TSPAN1, and TSPAN4 is increased in gastric cancer tissues and enhance the proliferation and invasion of gastric cancer cells, while CD81, CD82, TSPAN5, TSPAN9, and TSPAN21 are downregulated and suppress gastric cancer cell growth." (PMID 34222025, 2021).
breast carcinoma (12 papers, 2016 to 2025). "TSPAN1 expression in breast cancer was associated with increased migration and invasion." (PMID 40777026, 2025). "Tspan1 promotes the proliferation of cholangiocarcinoma and breast cancer by promoting the PI3K/AKT signaling pathway." (PMID 38649381, 2024). "To clarify the possible effects of TSPAN1 on breast cancer progression, we first evaluated its expression levels via bioinformation analysis." (PMID 34852709, 2021). "We detected the expression of E-cadherin and N-cadherin upon the transfection of TSPAN1 siRNA in breast cancer cells." (PMID 34852709, 2021). "We used two siRNAs of TSPAN1 to knockdown its expression in two types of breast cancer cells, MCF-7 and SK-BR-3 cells." (PMID 34852709, 2021). "This study aims to uncover the role of TSPAN1 in the progression of breast cancer and uncover the possible mechanism." (PMID 34852709, 2021). "Through the TCGA database, we noticed the transcript per million of TSPAN1 in breast cancer tissues was obviously higher." (PMID 34852709, 2021). "In the future study, we should confirm the effects of AKT inhibitors on TSPAN1-mediated breast cancer progression." (PMID 34852709, 2021). "Through CCK-8, wound closure, and transwell assays, we confirmed that TSPAN1 promoted the growth as well as motility of breast cancer cells." (PMID 34852709, 2021). "In this study, we identified a member of the TSPAN superfamily, TSPAN1, which was abnormally high expressed in human breast cancer cells and tissues." (PMID 34852709, 2021). "Then we performed the in vitro function experiments to investigate the effects of TSPAN1 on the growth and motility of breast cancer cells." (PMID 34852709, 2021). "For example, TSPAN13 has been shown to be a tumor suppressor gene in breast cancer, while TSPAN1 can inhibit the migration of alveolar epithelial cells and the EMT process." (PMID 32694936, 2020). "The expression pattern of TSPAN1 in prostate cancer was consistent with that from the breast cancer." (PMID 27556508, 2016). "The ablation of TSPAN1 suppressed the growth, and motility of breast cancer cells." (PMID 34852709, 2021). "Consistently, immunoblot results showed the high TSPAN1 expression in breast cancer cell lines." (PMID 34852709, 2021). "Our data suggest that TSPAN1 could serve as a promising therapeutic target for breast cancer treatment." (PMID 34852709, 2021). "In this study, we speculated that TSPAN1 could promote breast cancer by promoting the occurrence of EMT." (PMID 34852709, 2021). "Collectively, we thought TSPAN1 contributed to the growth and motility of breast cancer cells." (PMID 34852709, 2021). "Subsequently, we detected the effects of TSPAN1 on the PI3K/AKT pathway in breast cancer cells." (PMID 34852709, 2021). "TSPAN1 contributes to the growth and motility of breast cancer cells." (PMID 34852709, 2021). "We further examined the role of TSPAN1 in breast cancer by xenograft study in mice." (PMID 34852709, 2021). "Subsequently, we conducted CCK-8 assays to detect the effects of TSPAN1 on breast cancer growth." (PMID 34852709, 2021). "We then further detected the expression of TSPAN1 in breast cancer cell lines." (PMID 34852709, 2021). "Similarly, immunoblot assays confirmed the high TSPAN1 protein levels in 8 tumor tissues of breast cancer patients." (PMID 34852709, 2021). "TSPAN1 knockdown suppressed the growth, and motility of breast cancer cells." (PMID 34852709, 2021). "In summary, we thought TSPAN1 suppressed growth and motility of breast cancer via mediating EMT and PI3K/AKT pathway, and could serve as a potential target for treatment of breast cancer." (PMID 34852709, 2021). "Similarly, a study in breast cancer has shown that although TSPAN1 is upregulated in most primary tumours it is more likely to be downregulated in metastatic lesions." (PMID 28701765, 2017). "This suggests that TSPAN1 may regulate key processes that promote metastasis in breast cancer." (PMID 40777026, 2025).